ERBB4 (erb-b2 receptor tyrosine kinase 4)
Diseases named in the same sentence as ERBB4 in open-access papers (continued):
Sharing a sentence is not in itself a finding about the gene and the disease.
diabetes (9 papers, 2015 to 2024). "Surprisingly, we found lower serum concentration of ErbB4 in Sub1 combined with an improvement in several biochemical parameters of diabetes." (PMID 34646852, 2021). "Similarly, the phosphorylation ratio of ERBB2 is higher and that of ERBB3 and ERBB4 is lower in mice with diabetes compared with controls." (PMID 28496106, 2017). "Therefore, the level of fibrosis was enhanced by Erbb4-IR i diabetic kidneys." (PMID 34199672, 2021).
heart failure (9 papers, 2017 to 2025). Inability of the heart to pump blood at an adequate rate to meet tissue metabolic requirements. "Heart failure is a leading cause of morbidity and mortality, and ERBB4 signaling has been proposed as a potential therapeutic target." (PMID 39794341, 2025). "Notably, mouse studies identified that cardiomyocyte specific loss of NRG3 receptors (ErbB2 and ErbB4) results in spontaneous heart failure suggesting a potential role for NRG3 in regulating cardiac homeostasis." (PMID 35959412, 2022). "We found similar, although less robust, patterns for both ERBB2 and ERBB4, with participants in the lowest quartile having higher risks of incident heart failure and cardiovascular mortality than some other quartiles when adjusted for age, sex, BMI, and DM." (PMID 39180332, 2024). "The NRG-1/ErbB4 signalling system is critical for the mitigation of heart failure, an outcome of late-stage CAD." (PMID 37336921, 2023). "This is an interesting finding, because the inhibition of the ErbB4 gene by DOX was postulated to be involved in the development of heart failure in DOX-treated cancer patients." (PMID 28052002, 2017). "This study shows that small-molecule ERBB4 activation is feasible and may lead to a novel class of drugs for treating heart failure." (PMID 39794341, 2025). "ERBB2 (score 8) and ERBB4 (score 7), both Neuregulin-1 receptors, are involved in cardiac regeneration after injury, and Neuregulin-1 itself is a therapeutic target for heart failure." (PMID 40791945, 2025). "Proteins ErbB2 and ErbB4, downstream of NRG-1, have demonstrated mitigation of heart failure and, when activated to heterodimerize, trigger MAPK signaling." (PMID 37856516, 2023).
osteosarcoma (9 papers, 2014 to 2025). A usually aggressive malignant bone-forming mesenchymal neoplasm, predominantly affecting adolescents and young adults. "ErbB4 and STAT3 confer osteosarcoma chemoresistance via the inhibition of apoptosis." (PMID 37107591, 2023). "The ERBB4–ICD complex is inhibited both by Hippo signaling and by WWOX oxidoreductases, which compete with ERBB4–ICD for the binding to YAP, thus potentially accounting for WWOX tumor-suppressive activities in osteosarcomas." (PMID 34439395, 2021). "ERBB4 leads to activation of PI3K-AKT, focal adhesion kinase (FAK) and the RAC1 GTPase, a mediator of cell migration and invasion, pathways that are already been described in osteosarcoma pathogenesis." (PMID 29113313, 2017).
myocardial infarction (8 papers, 2015 to 2025). Gross necrosis of the myocardium, as a result of interruption of the blood supply to the area, as in coronary thrombosis. "Our previous works demonstrated the upregulation of Hippo/YAP signaling pathway in regenerative pig hearts that underwent myocardial infarction on P1, as well as ERBB4 in ARP1P28 hearts at the protein level." (PMID 38288246, 2023). "Another study showed that aged MSCs overexpressing ERBB4 reduced myocardial infarct size and improved cardiac function." (PMID 33639970, 2021). "In wild-type mice, EF-1 inhibits angiotensin-II-induced fibrosis in males and females and reduces heart damage caused by doxorubicin and myocardial infarction in females, but not in Erbb4-null mice." (PMID 39794341, 2025). "In this connection, we aimed to determine whether overexpression of ERBB4 in MSCs can enhance their cardio-protective effects following myocardial infarction." (PMID 25996292, 2015). "NRG1, MSCs or MSC-ERBB4 (MSC with ERBB4 overexpression), were transplanted into mice following myocardial infarction." (PMID 25996292, 2015). "Researchers in the recent study investigated whether ERBB4 rejuvenates aged MSC and how ERBB4 enhances the therapeutic efficacy of aged MSC in treating myocardial infarction (MI)." (PMID 34250732, 2021). "Overexpression of Erb-B2 receptor tyrosine kinase 4 (ERBB4) can rejuvenate aged MSCs and stimulate angiogenesis by regulating the PI3K/AKT and the MAPK/ERK pathways, leading to increased therapeutic effects for myocardial infarction." (PMID 31965214, 2020).
autism (7 papers, 2012 to 2024). Persistent deficits in social interaction and communication and interaction as well as a markedly restricted repertoire of activity and interest as well as repetitive patterns of behavior. "Several candidate autism susceptibility genes were hypermethylated (P <0.05) in the HMFA, including Shank3, Cacana1g, Gtf2i, Rapgef4, and Nbea in male offspring and Ext1, Ube3a, Erbb4, Grip1, Grm8, Reeln, Shank3, and Rbfox1 in female offspring." (PMID 24484737, 2014). "In a recent study, Yanan Deng reported that inhibition of the Notch pathway using DAPT alleviated autism-like behaviors and reduced NRG1 and phosphorylated ErbB4 levels, suggesting the involvement of the Notch1/Hes1 pathway in regulating the NRG1/ErbB4 pathway in autism." (PMID 38791584, 2024).
cervical cancer (7 papers, 2014 to 2025). A primary or metastatic malignant neoplasm involving the cervix. "Data from the Cancer Genome Atlas showed that the loss of ERBB4 gene copy numbers was found in different cancer types, including esophageal, lung, bladder and cervical carcinoma." (PMID 34620079, 2021). "Several reports have suggested that patients with ERBB4 mutations may respond to ICIs treatment in esophageal cancer and cervical cancer." (PMID 34620079, 2021). "Moreover, network analysis showed that almost all genes that interacted with YAP, including other YAP-associated transcriptional factors such as ERBB4, Runx1, and Runx2, are up-regulated in various degrees in examined cervical cancer cases." (PMID 26417066, 2015).
endometrial cancer (7 papers, 2010 to 2023). Primary or metastatic malignant neoplasm involving the endometrium (mucous membrane that lines the endometrial cavity). "employed transcriptome sequencing technology to analyze 5 pairs of endometrial cancer tissues and normal endometrial tissues, revealing downregulation of ID1, IGF1, GDF7, SMAD9, TGF-β, and WNT4 expression alongside upregulation of GDF5, INHBA, and ERBB4 in endometrial cancer." (PMID 38239355, 2023). "In the present study, we observed that ERBB4 was highly expressed in endometrial cancer compared to normal endometrial tissue; thus, it may provide a clue for endometrial carcinogenesis and may serve as a novel target for treatment." (PMID 34925436, 2021). "In this study, KLE cells (derived from undifferentiated endometrial carcinoma) were used as the positive controls in an analysis of the cellular expression of EGFR and ErbB4." (PMID 37231448, 2023).
Ewing sarcoma (7 papers, 2010 to 2019). A small round cell tumor that lacks morphologic, immunohistochemical, and electron microscopic evidence of neuroectodermal differentiation. "Together, our studies show that the EWS/Fli1-repressed miR-193b is growth suppressive in Ewing Sarcoma, and identify ErbB4 as a target gene and candidate mediator of this growth suppression." (PMID 28542597, 2017). "As miR-193b has been implicated in metastasis suppression in a number of other cancers, it will be of interest in future studies to examine the potential role of the miR-193b/ErbB4 axis in Ewing Sarcoma metastasis." (PMID 28542597, 2017). "Our studies identify miR-193b as a new growth-suppressive microRNA in Ewing Sarcoma, and provide evidence in support of ErbB4 as a mediator of this growth inhibition." (PMID 28542597, 2017). "It has been shown that ERBB4 is overexpressed in Ewing Sarcoma cell lines derived from chemoresistant or metastatic Ewing sarcoma, a tumor of the bone." (PMID 29113313, 2017). "In closing, our studies identify miR-193b as a new growth-suppressive miR in Ewing Sarcoma, and ErbB4 as a relevant candidate target potentially contributing to its growth-suppressive effects." (PMID 28542597, 2017). "Biochemical and histological/immunohistochemical ex vivo analyses confirmed a reduced activation of ERBB4, EGFR, INSR, IGF1R, associated with apoptosis induction and angiogenesis inhibition in a drug-treated Ewing's sarcoma family tumor xenograft." (PMID 27374103, 2016). "Recent evidence suggests involvement of RTKs such as PDGFR, c-Met, Axl, IGF1-R, EphB4 and ErbB4 as driver kinases in different sarcoma subtypes including synovial sarcoma, Ewing sarcoma as well as malignant peripheral nerve sheath tumor (MPNST)." (PMID 26675259, 2016). "Interestingly, ErbB4 had previously been identified as a suppressor of anoikis in Ewing Sarcoma, a phenotype pertinent to anchorage-independent growth." (PMID 28542597, 2017). "Thus, negative regulation of ErbB4 expression likely contributes to growth inhibition by miR-193b in Ewing Sarcoma." (PMID 28542597, 2017). "To determine whether miR-193b indeed regulates ErbB4 expression in Ewing Sarcoma, we examined the effects of stable miR-193b expression on ErbB4 protein levels." (PMID 28542597, 2017). "Our studies identify ErbB4 as a relevant miR-193b target in Ewing Sarcoma." (PMID 28542597, 2017). "Interestingly, other studies have also identified ErbB4 as a metastasis promoter in Ewing Sarcoma." (PMID 28542597, 2017). "In Ewing tumor spheroids, E-cadherin cell-cell contacts may activate the ErbB4 RTK signal pathway." (PMID 20398401, 2010).
Intellectual disability (7 papers, 2018 to 2025). "Thus far there is only a single case report in the literature of a heterozygous ERBB4 deletion in a patient with intellectual disability (ID)." (PMID 33603162, 2021).
triple-negative breast carcinoma (7 papers, 2016 to 2022). An invasive breast carcinoma which is negative for expression of estrogen receptor (ER), progesterone receptor (PR), and human epidermal growth factor receptor 2 (HER2). "Clinical studies suggested that to the patients with advanced stage or triple-negative breast cancer, increased expression of ErBb4 is associated with poor prognosis." (PMID 33246450, 2020). "Although ERBB4 as a prognostic marker has been debated, the morphology of the solid type is similar to invasive ductal carcinoma of triple-negative breast carcinoma compared to colorectal adenocarcinoma." (PMID 33446784, 2021). "Our research suggests that ERBB4 expression is a useful prognostic marker and may be useful to predict response to therapy for triple negative breast cancer." (PMID 26907936, 2016). "Moreover, we expect that further clinical trials on RTKs would benefit patients suffering from refractory triple negative breast cancer with high ERBB4 expression." (PMID 26907936, 2016). "In conclusion, our research suggests that ERBB4 expression is a valuable prognostic marker and may be useful to predict response to therapy for triple negative breast cancer." (PMID 26907936, 2016). "To date, a potential protective or promoting role for ERBB4 in basal and/or triple-negative breast cancers is a debated topic, and our data do not support this hypothesis." (PMID 35664762, 2022).
asthma (6 papers, 2013 to 2024). "The variant with the most evidence of association with asthma was rs13008370 in the ERBB4 gene on chromosome 2 (Posterior probability 47%, Bayes Factor: 157)." (PMID 24152222, 2013). "Other SNPs within ERBB4 were associated with asthma included rs11680307 (Bayes Factor: 42), rs1521658 (Bayes Factor: 26), and rs6435692 (Bayes Factor: 4)." (PMID 24152222, 2013). "In terms of ErbB4, there is limited evidence available, but some study suggested the relationship with ErbB4 and severe asthma pathogenesis." (PMID 33217964, 2020). "The underlying key genes in asthma pathogenesis and those regulated by treatment including Adipoq, HMOX1, SPP1, Cyp2e1, TNC, MB, MPO, Col9a1, Ckmt2, and Erbb4 were taken as examples to illustrate the positions and relationships with other points and midline in the figure." (PMID 33531915, 2021). "The relevance between ErbB3 and ErbB4 and asthma pathogenesis is an emerging research field." (PMID 33217964, 2020). "From these result about ErbB4, ErbB4 would contribute to asthma pathogenesis in some degree, especially in severe asthmatics along with use of inhaled corticosteroid, but further basic and clinical studied need to be established for the clinical implication of ErbB4 and asthma." (PMID 33217964, 2020). "The relevance between asthma pathogenesis and ErbB4 has not been well described, but some evidence has been reported regarding the relationship between ErbB4 and asthma." (PMID 33217964, 2020). "Our findings support a role for enhanced EGFR signalling in asthma airway remodelling and might suggest a functional involvement of ERBB2, also known as human epidermal growth factor receptor 2 (HER2), and ERBB4, also known as HER4, in its pathogenesis." (PMID 39401856, 2024).
colitis (6 papers, 2015 to 2025). Inflammation of the colon. "Loss of macrophage ErbB4 exacerbated the severity of experimental colitis and promoted macrophage accumulation in tissue." (PMID 33826403, 2021). "To test the impact of loss of NRG4/ErbB4 signaling specifically in macrophages during colitis, we used ErbB4myeKO mice." (PMID 33826403, 2021). "Our data show that pro-inflammatory activation of macrophages induces robust ErbB4 receptor expression, and acute colitis is associated with recruitment of ErbB4-expressing macrophages." (PMID 28230865, 2017). "ERBB4 knockout mice have increased colitis, likely mediated by increased macrophage activation and inflammatory mediator production." (PMID 40625733, 2025). "Next, we evaluated the colitis severity, anxiety-like behaviors, levels of stress-related hormones, and expression of ErbB4 in SiHo WT mice, SiHo ERβ−/− mice, CoHo WT, and CoHo ERβ−/− mice after DSS treatment." (PMID 36175956, 2022). "NEW & NOTEWORTHY Proinflammatory macrophages are essential drivers of colitis and express the growth factor receptor ErbB4." (PMID 33826403, 2021). "Taken together, these findings demonstrate that NRG4/ErbB4 signaling in macrophages restrains the proinflammatory tone of these cells and is an important limiting regulator of colitis severity." (PMID 33826403, 2021). "In vivo, ErbB4myeKO mice subjected to acute DSS colitis showed exaggerated disease, and ErbB4 myeloid knockout in the IL 10-KO chronic colitis model accelerated disease onset." (PMID 33826403, 2021). "Proinflammatory macrophages are essential drivers of colitis and express the growth factor receptor ErbB4." (PMID 33826403, 2021). "As inflammatory macrophages are central to IBD pathology, identification of an ErbB4-mediated feedback mechanism that limits or alters their activity advances our understanding of innate immune regulation in colitis." (PMID 28230865, 2017). "However, multiple tissues in the colon express the NRG4 receptor, ErbB4, thus making the direct role of ErbB4 in macrophages during colitis unclear." (PMID 33826403, 2021). "ErbB4 activation with exogenous ligand administration was therapeutic in acute murine colitis." (PMID 28230865, 2017). "To determine whether macrophage-expressed ErbB4 has a role in intestinal inflammatory disease in vivo, we tested whether ErbB4 is expressed on recruited macrophages in the dextran sodium sulfate (DSS) experimental model of murine colitis." (PMID 28230865, 2017). "In vivo, ErbB4 was highly expressed on pro-inflammatory macrophages but not neutrophils during experimental DSS colitis in C57Bl/6 mice." (PMID 28230865, 2017). "However, the acute functional roles for endogenous ErbB4 signaling in macrophages and how these influence colitis have not been identified." (PMID 33826403, 2021). "As macrophages are the only myeloid cells on which we observed robust ErbB4 expression, together with our NRG4 rescue experiment results these findings support the idea that ErbB4 signaling in macrophages is a selective anti-inflammatory feedback mechanism in colitis." (PMID 28230865, 2017). "Furthermore, we detected only low levels of ErbB4 expression on Ly6G+ granulocyte/neutrophils and did not see induction on this population during DSS colitis." (PMID 28230865, 2017).
esophageal squamous cell carcinoma (6 papers, 2014 to 2025). Esophageal squamous cell carcinoma (ESCC) is a type of esophageal carcinoma (EC) that can affect any part of the esophagus, but is usually located in the upper or middle third. "In a study on esophageal squamous cell carcinoma, miR-302b was shown to downregulate expression of ErbB4, a tumor growth and metastatic factor, as well as induce apoptosis in cancer cells." (PMID 40777372, 2025). "Besides, inhibition of Smad3-dependent long non-coding RNA erb-b2 receptor tyrosine kinase 4 intracellular domain fragment (Erbb4-IR) suppresses the proliferation of esophageal SCC by upregulating the tumor suppressor gene miRNA-145 to activate cancer cells apoptosis." (PMID 37205317, 2023). "In addition, a novel Smad3-dependent long non-coding RNA Erbb4-IR showed various actions in prostate and esophageal squamous cell carcinoma, where one of the actions is to inhibit apoptosis by downregulating tumor suppressor miRNA-145, thus promoting cancer cell proliferation." (PMID 34299192, 2021). "Researchers have shown that miR-302b can suppress tumor proliferation of esophageal squamous cell carcinoma (ESCC) via downregulation of the Erb-b2 receptor tyrosine kinase 4 (ERBB4) gene." (PMID 29482609, 2018). "ErbB4 expression has been noted in various tumors, but its regulatory mechanism in esophageal squamous cell carcinoma (ESCC) remains unclear." (PMID 24438167, 2014).
invasive breast carcinoma (6 papers, 2009 to 2023). A carcinoma that infiltrates the breast parenchyma. "ERBB4 loss is most frequently found in invasive breast carcinoma and prostate adenocarcinoma, while ERBB2 loss is found in ovarian high-grade serous carcinoma and invasive breast carcinoma." (PMID 36790480, 2023).
lymph node metastasis (6 papers, 2011 to 2023). "The Erb-b2 receptor tyrosine kinase 4 (ErbB4) gene, also known as human epidermal growth factor receptor 4 (HER4), has been reported as overexpressed in EC tissue and is also associated with TMN stage and lymph-node metastasis." (PMID 30322005, 2018).
anaplastic large cell lymphoma (5 papers, 2016 to 2025). Anaplastic large cell lymphoma (ALCL) is a rare and aggressive peripheral T-cell non-Hodgkin lymphoma, belonging to the group of CD30-positive lymphoproliferative disorders, which affects lymph nodes and extranodal sites. "The reactivation of ancient LTR has also been associated with the novel oncogenic transcription of ERBB4 in ALK-negative anaplastic large cell lymphoma (ALCL)." (PMID 28471386, 2017). "Reactivation of the ancient LTR was found to promote a novel oncogenic transcript of ERBB4 in ALK-negative anaplastic large cell lymphoma (ALCL)." (PMID 41459148, 2025). "Ectopic coexpression of ERBB4 and COL29A1 genes was detected in 24 % of ALK-negative anaplastic large cell lymphoma (ALCL) patients." (PMID 26949423, 2016).